ADM2 (adrenomedullin 2)
Description:
Intermedin/ADM2 is a peptide hormone that plays a role as physiological regulator of gastrointestinal and cardiovascular bioactivities mediated by the CALCRL-RAMPs receptor complexes. Activates the cAMP-dependent pathway through interaction with CALCRL-RAMP3 receptor complex.
Synonyms: AM2; FLJ21135; dJ579N16.4
Tractability: Small molecule: a high-quality ligand is known. Antibody: UniProt places it where antibodies can reach, with high confidence; its Gene Ontology location is reachable by antibodies, with high confidence; UniProt predicts a signal peptide or a membrane-spanning region. PROTAC: a small molecule that binds it is known.
Target class: Secreted protein
Gene: Protein-coding gene on chromosome 22 (50,481,543 to 50,486,440, forward strand). Ensembl gene ENSG00000128165.
Subcellular location: Secreted
Pathways (Reactome):
Signal Transduction: Calcitonin-like ligand receptors; G alpha (s) signalling events
Gene Ontology:
Molecular function: hormone activity; protein-containing complex binding
Biological process: adrenomedullin receptor signaling pathway; angiogenesis; positive regulation of angiogenesis; positive regulation of gene expression; protein phosphorylation; adenylate cyclase-activating G protein-coupled receptor signaling pathway; positive regulation of heart rate; regulation of systemic arterial blood pressure; regulation of urine volume; feeding behavior; negative regulation of blood pressure
Cellular component: extracellular region
Genetic constraint (gnomAD): Loss-of-function variants: 9 observed, 6.7 expected, observed/expected ratio (o/e) 1.34, 90% interval 0.79 to 1.9. That is too few expected variants to judge how well the gene tolerates losing a copy. Missense variants: 236 observed, 164.3 expected, observed/expected ratio (o/e) 1.44, 90% interval 1.29 to 1.6. Synonymous variants: 123 observed, 76.1 expected, observed/expected ratio (o/e) 1.62, 90% interval 1.39 to 1.87.
Homologues: Orthologues: macaque ADM2 (95% identical), chimpanzee ADM2 (78% identical), dog ADM2 (68% identical), pig ADM2 (68% identical), mouse Adm2 (65% identical), rat Adm2 (64% identical), zebrafish adm2a (34% identical). Paralogues in human: ADM (18% identical).
Diseases named in the same sentence as ADM2 in open-access papers:
ADM2 is named in the same sentence as 53 diseases in open-access papers, as found by Europe PMC text mining. Sharing a sentence is not in itself a finding about the gene and the disease. The quoted sentences say what the papers report.
breast carcinoma (4 papers, 2021 to 2026). "Mapping SNPs to genes showed that two genes (SPP1 and ADM2) were significantly upregulated in breast cancer." (PMID 41056019, 2026). "ADM2 promotes the growth, migration, and invasion of breast cancer cells by inducing Src kinase phosphorylation, thereby triggering c-Myc transcription." (PMID 41056019, 2026). "Knocking down ADM2 significantly inhibited the invasive ability of breast cancer cell lines BT-549 and MDA-MB-231." (PMID 41150812, 2025). "In order to further explore the effect of ADM2 and RAMP2 on breast cancer cells, siRNAs of ADM2 and the overexpression vector for RAMP2 were constructed and transfected into BT-549 and MDA-MB-231 breast cancer cell lines, respectively." (PMID 41150812, 2025). "After constructing siRNAs targeting ADM2 and RAMP2 overexpression plasmids, our results revealed that downregulating ADM2 expression significantly inhibited the proliferation and infiltration of breast cancer cells." (PMID 41150812, 2025). "Based on our results, we speculate that ADM2 can be secreted by tumor stromal cells and bind to G protein-coupled receptors of breast cancer tumor cells through paracrine methods, thereby promoting the proliferation and invasion of breast cancer cells." (PMID 41150812, 2025). "Venn analysis of PMRGs and upregulated DEGs revealed two key PMRGs that were upregulated in breast cancer, namely SPP1 and ADM2." (PMID 41056019, 2026). "Subsequently, the role of these driver genes in DCIS progression was validated through ADM2 knockdown and RAMP2 overexpression, which, as expected, inhibited the proliferation and migration of breast cancer cell lines." (PMID 41150812, 2025). "CCK-8 assays demonstrated that ADM2 knockdown significantly suppressed the proliferation of BT-549 and MDA-MB-231 cells, while overexpression of RAMP2 also inhibited proliferation across multiple breast cancer cell lines." (PMID 41150812, 2025). "Gene set enrichment analysis (GSEA) revealed the biological functions of RAMP2 and ADM2, while in vitro functional assays demonstrated that ADM2 knockdown and RAMP2 overexpression in breast cancer cell lines significantly suppressed cellular proliferation and invasion." (PMID 41150812, 2025). "Therefore, we further evaluated the effects of ADM2 and RAMP2 on the biological functions of breast cancer cell lines in vitro." (PMID 41150812, 2025). "adrenomedullin-2 (ADM2) is a hypoxia-inducible endothelial peptide that stabilizes pulmonary microvascular.CLIC6 is a member of the intracellular chloride channel, one of the dopamine receptor-mediated signalling pathways, and is differentially expressed in breast cancer." (PMID 34804921, 2021).
Insulin resistance (4 papers, 2021 to 2025). Increased resistance towards insulin, that is, diminished effectiveness of insulin in reducing blood glucose levels. "Treatment with recombinant ADM2 inhibits obesity-induced insulin resistance in mice through deactivating adipose CD4+ T cells." (PMID 37538245, 2023). "ADM2 affects the beiging of white adipose tissues and insulin resistance, and it has been found to correlate with age and memory retention in mice." (PMID 37538245, 2023). "Adrenomedullin 2 (ADM2), an endogenous bioactive peptide belonging to the calcitonin gene-related peptide family, exhibits various biological activities associated with the inhibition of inflammation and reduction of insulin resistance." (PMID 33985585, 2021). "In skeletal muscle and adipose tissue, ADM2 activates cAMP/PKA and AMPK crosstalk to stimulate GLUT4 membrane translocation and exerts anti-inflammatory effects that improve insulin resistance." (PMID 41465308, 2025).
Obesity (4 papers, 2022 to 2023). Accumulation of substantial excess body fat. "In patients with obesity, ADM2 signaling is found to be suppressed in adipose tissues and is associated with lower receptor expression and ligand availability." (PMID 37538245, 2023).
thyroid cancer (4 papers, 2020 to 2025). "Furthermore, metabolic stressors were shown to increase ADM2 expression in a murine thyroid cancer mouse model, and elevated circulating ADM2 was associated with higher body mass index and fasting glucose levels, implicating ADM2 in the metabolic dysregulation observed in thyroid cancer." (PMID 40558487, 2025). "A recent investigation of a mouse thyroid cancer model with thyrocyte-specific activation of BRAFV600E revealed that ADM2 was upregulated in thyroid tumors." (PMID 40076501, 2025). "Interestingly, circulating ADM2 levels are elevated in patients with both thyroid cancer and type 2 diabetes compared to those with thyroid cancer alone." (PMID 40558487, 2025). "This study showed that the gene expression of Adm2 was increased only by neonatal irradiation and continued to be upregulated even at 6 months after exposure, suggesting the critical role of Adm2 in the development of thyroid cancer by childhood irradiation." (PMID 40076501, 2025). "For Adm2, IHC studies confirmed the reduced expression in the PVPV-Akt KO mouse thyroids and an increase in expression with invasion in human thyroid cancer, consistent with potential regulation by Akt signaling." (PMID 33110146, 2020).
glioma (3 papers, 2021 to 2023). A benign or malignant brain and spinal cord tumor that arises from glial cells (astrocytes, oligodendrocytes, ependymal cells). "The ADM2 expression was positively correlated with the malignancy grade in gliomas." (PMID 34961815, 2021). "Adrenomedullin 2, another CGRP member, increased glioma cell invasion and proliferation via enhancing the formation of filopodia, which depends on the activation of Erk1/2 pathway." (PMID 36183123, 2022).
Hypertension (3 papers, 2021 to 2025). The presence of chronic increased pressure in the systemic arterial system. "In addition, expression of ADM2 and its receptors is increased in the heart, plasma, and cardiovascular tissue in pathological conditions such as hypertension, atherosclerosis, or congestive heart failure." (PMID 34437633, 2021). "Indeed, it has been reported that expression of ADM2 and its receptors in the heart increases under pathological conditions such as congestive heart failure and hypertension." (PMID 34437633, 2021).
lung carcinoma (2 papers, 2021). "For other IRGs, such as LGR4, GDF10, GREM1, IL20RB, INHA, VIPR1, and ADM2, they had been verified to participate in carcinogenesis and affect patients’ prognoses in other cancers, although the relevant studies were rare in lung cancer." (PMID 33386920, 2021). "Compared with normal tissues, the expression of ADM2, CLIC6, KIF20A, LAD1, MUC5B, and TNS4 was up-regulated, and the expression of ATG16L2, KCNK3, MAFF, NKD1, and SPATA13 was down-regulated in lung cancer tissues." (PMID 34804921, 2021).
asthma (1 paper, 2025). "High PPG exposure was associated with lower DNAm at cg12318501 (ZNF99, β = −0.029, p = 0.032) and cg00929606 (ADM2, β = −0.023, p = 0.008), which subsequently was associated with decreased odds of asthma (OR = 0.11, 95% CI 0.02–0.53, p = 0.006; OR = 0.14, 95% CI 0.02–1.00, p = 0.049)." (PMID 40136322, 2025).
cerebral infarction (1 paper, 2024). An ischemic condition of the brain, producing a persistent focal neurological deficit in the area of distribution of the cerebral arteries. "Hirose found a positive association between the rs3840963 polymorphic locus of ADM2 and the development of asymptomatic cerebral infarction and cerebral white matter lesions." (PMID 39697434, 2024).
chronic kidney disease (1 paper, 2020). Impairment of the renal function secondary to chronic kidney damage persisting for three or more months. "Specifically, the deletion/deletion carriers of rs3840963 of Adrenomedullin 2 (ADM2), encoding proteins that regulate cardiovascular homeostasis and prolactin release, suffered from higher risk of chronic kidney disease, CI and WMH." (PMID 33352859, 2020).
immunodeficient diseases (1 paper, 2022). "The functional capacities of the highly expressed DEGs in the Chinese Simmental cattle mainly focused on inflammatory diseases (CXCL9 and FCRL1), immunodeficient diseases (ADM2, CCL5, and CAMKV), carcinoma (CXCL11, JAKMIP2, GZM, and DNAAF1), and GTP binding and GTPase activity (NUGGC)." (PMID 35495650, 2022).
infertile (1 paper, 2022). "Further studies of the role of ADM2 signaling during folliculogenesis may facilitate our ability to improve follicle development in infertile patients." (PMID 36452323, 2022). "Therefore, the recruitment of growing follicles is regulated by multiple negative regulatory pathways, and future studies of these pathways may reveal how Adm2 disruption in oocytes enhances ovulation rate, and facilitate our ability to improve follicle development in infertile patients." (PMID 36452323, 2022).
pancreatic adenocarcinoma (1 paper, 2020). "For example, ADM2, one risk biomarker in the gene signature, was reported to predict poor survival in patients with pancreatic adenocarcinoma." (PMID 32370292, 2020).
pulmonary hypertensive (1 paper, 2025). "An in vitro study found that adrenomedullin 2 is an important vasorelaxant in the pulmonary vascular system, indicating a protective effect in hypoxia-induced pulmonary hypertensive rats." (PMID 40136322, 2025).
renal fibrosis (1 paper, 2017). A final common manifestation of a wide variety of chronic kidney diseases characterized by glomerulosclerosis and tubulointerstitial fibrosis. "Intermedin [IMD, adrenomedullin-2 (ADM-2)] attenuates renal fibrosis by inhibition of oxidative stress." (PMID 28697727, 2017).
cancer (14 papers, 2018 to 2025). A tumor composed of atypical neoplastic, often pleomorphic cells that invade other tissues. "Recently, several groups revealed that adrenomedullin 2 (ADM2), an endogenous bioactive peptide belonging to the calcitonin gene-related peptide family is an inducible gene in response to mitochondrial stress caused by inhibition of mitochondrial respiration chain in human cancer cell lines." (PMID 30307158, 2018). "Among these 4 genes, we performed IHC to confirm protein expression patterns for two genes, Adm2 and Cd209a, due to their expression in human tissues and their potential roles in cancer progression." (PMID 33110146, 2020). "HELZ2, ADM2 are also related with prognosis of various types of cancer." (PMID 37955724, 2023). "ADM-2 is an ortholog of the human ADAM9, which is implicated in inflammation, cancer, and AD by cleaving the APP, but whether ADAM9 plays a potential role in Aβ removal is unknown." (PMID 37728486, 2023). "ADM2 stimulates Protein Kinase A and ERK pathways in vitro, promoting cancer cell proliferation and migration." (PMID 41353477, 2025). "Based on the pan-cancer analysis of drug sensitivity datasets, ADM and ADM2 expression levels were significantly correlated with sensitivity of various medications in both the GDSC and CTRP databases, with ADM showing a broader and more significant correlation." (PMID 40529377, 2025). "The roles played by the peptides belonging to the tachykinin (neurokinin A and B) and calcitonin/calcitonin gene-related peptide (adrenomedullin, adrenomedullin 2, amylin, and calcitonin gene-related peptide (CGRP)) peptide families in cancer development are reviewed." (PMID 36980580, 2023).
tumor (8 papers, 2020 to 2025). "ADM2 can negatively regulate gamma delta T cell, a T cell subpopulation that inhibits tumor occurrence and development." (PMID 41150812, 2025). "Subsequently, ADM2 and RAMP2 were identified as “tumor progression-associated genes” (TPAGs), as multiple experimental approaches revealed significant alterations in their expression during DCIS progression." (PMID 41150812, 2025). "The HOXA4, CYP4F12, and ADM2 were positively correlated with the immune and stromal score but negatively correlated with tumor purity." (PMID 37955724, 2023). "CGRP, ADM, and ADM2 have been shown to promote vascular development and tumor growth." (PMID 36569288, 2022). "Adrenomedullin 2 (AM2/intermedin) and CGRP act as tumor survival/growth factors promoting lymphangiogenesis and angiogenesis." (PMID 36980580, 2023).
metabolic disorders (4 papers, 2021 to 2023). "Adrenomedullin 2 (ADM2) is an endogenous peptide belonging to the calcitonin family that decreases significantly under diabetic conditions, and the reduction in ADM2 levels is associated with DM-related metabolic disorders." (PMID 35418946, 2022). "A previous study shown that systemic ADM2 levels of diabetic rats were significantly decreased, indicating that there is a relationship between low ADM2 levels and DM-related metabolic disorders." (PMID 35573673, 2022). "A previous study reported that systemic ADM2 levels were significantly decreased in diabetic rats compared to healthy individuals, indicating a relationship between low ADM2 levels and DM-related metabolic disorders." (PMID 33985585, 2021).
infection (1 paper, 2022). The state of being infected such as from the introduction of a foreign agent such as serum, vaccine, antigenic substance or organism. "The expression of pathway genes (TIRB3, ADM2, PCK2) that bind to ubiquitin-like protein ligase and transcriptional corepressor activity were significantly down-regulated after infection by C. perfringens, and significantly up-regulated after 2′-FL treatment." (PMID 35458130, 2022).
ADM2 also shares sentences with these, for which no sentence is quoted: cardiovascular disease (2 papers); migraine (2); prostate carcinoma (2); thyroid tumor (2); anaplasmosis (1); astroglioma (1); atherosclerosis (1); babesiosis (1); bovine diseases (1); brucellosis (1); choriocarcinoma (1); congestive heart failure (1); COVID-19 (1); diabetes (1); Ewing sarcoma (1); fetal growth restriction (1); glioblastoma multiforme (1); hepatocellular carcinoma (1); hypotension (1); leptospirosis (1); melanoma (1); metabolic syndrome (1); nasopharyngeal carcinoma (1); neuroendocrine tumors (1); oropharyngeal squamous cell carcinoma (1); ovarian carcinoma (1); pancreatic cancer (1); periodontitis (1); phaeochromocytoma (1); preeclampsia (1).
A further 4 diseases each share a sentence with ADM2 in 1 paper.